INS (insulin)
Diseases named in the same sentence as INS in open-access papers (continued):
Sharing a sentence is not in itself a finding about the gene and the disease.
type 1 diabetes (continued). "Type 1 diabetes (T1D) is a metabolic disease characterized by an autoimmune destruction of the pancreatic cells responsible for insulin production and thus compromises the complex physiological feedback systems regulating blood glucose (BG) homeostasis." (PMID 33673415, 2021). "Type 1 diabetes (T1D) is a chronic autoimmune disease characterized by insulin-producing pancreatic beta cells destroyed by autoreactive T cells." (PMID 35111148, 2021). "In the present study, a distinct gut region-dependent TNFα induction was revealed in type 1 diabetic rats and segment-specific effects of immediate insulin treatment on TNFα expression was also observed." (PMID 34572059, 2021). "Type 1 diabetes mellitus (T1DM) is a chronic metabolic disorder characterized by the insufficient production of endogenous insulin due to pancreatic beta cells autoimmune destruction which is associated with multiple clinical manifestations." (PMID 34886337, 2021). "The workflow was implemented in R and evaluated using a systematic review of insulin formulations for type-1 diabetes (14,314 abstracts) and a scoping review of knowledge-synthesis methods (17,200 abstracts)." (PMID 34039433, 2021). "For example, the standard treatment for Type 1 Diabetes is delivery of exogenously produced insulin, and rheumatoid arthritis is treated via delivery of systemic immunosuppressant drugs such as steroids." (PMID 33732229, 2021). "The glycemic level is essentially controlled by insulin, and is known to be associated with regular BMD and reductions in bone resorption in patients with type 1 diabetes." (PMID 34440530, 2021). "Insulin also positively regulated ACSS2 expression, while streptozotocin treatment to induce type I diabetes and decrease insulin levels decreased ACSS2 expression." (PMID 33917812, 2021). "For employed people with type 1 diabetes, health management comprises controlling blood sugar levels and the intake of insulin." (PMID 34803795, 2021). "The aim of this study was to compare individuals with type 1 diabetes using either an insulin pump (CSII) or a basal bolus regime with insulin pens (ICT) in routine care." (PMID 34301317, 2021). "Intensified insulin therapy (ICT) and insulin pump therapy (continuous subcutaneous insulin infusion; CSII) are the most common insulin therapies for people with type 1 diabetes." (PMID 34301317, 2021). "In the case of type 1 diabetes the insulin replacement therapy is necessary and involves multiple daily injections of insulin or continuous subcutaneous insulin infusion." (PMID 33467194, 2021). "In type 1 diabetes, insulin remains the mature therapeutic cornerstone; yet, the increasing number of individuals developing type 1 diabetes (predominantly children and adolescents) still face severe complications." (PMID 33595677, 2021). "ZnT8 is highly specific to pancreatic insulin-producing beta cells, and autoantibodies to the same are found in individuals with type 1 diabetes." (PMID 34836302, 2021). "Type-1 diabetes mellitus (T1DM) is a disease in which the pancreas produces insufficient insulin to control blood sugar levels for glucose homeostasis." (PMID 34072062, 2021). "Remarkably these neoepitopes, called hybrid insulin peptides, or HIPs, are recognized by pathogenic CD4+ T cells in the NOD mouse and human pancreatic islet-infiltrating T cells in people with type 1 diabetes." (PMID 33995402, 2021). "Clinical symptoms usually develop when most functional beta cell mass has been lost, by which time individuals with type 1 diabetes depend on exogenous insulin and lifestyle management as the mainstays of treatment." (PMID 33145642, 2021). "The flexible insulin therapy is considered as a crucial turning point in the management of type 1 diabetes." (PMID 34909088, 2021). "Patients with type 1 diabetes mellitus (T1DM) under good control with insulin have comparable lipid profiles to the general population." (PMID 34368411, 2021).
type 1 diabetes (continued). "Type 1 diabetes (T1D) is an autoimmune disease targeting insulin-producing pancreatic β-cells specifically mediated by T lymphocyte." (PMID 34707607, 2021). "On the other hand, in type-1 diabetes, the pancreatic beta cells which are responsible for insulin production are either damaged or unable to produce enough insulin for the glucose uptake." (PMID 34443593, 2021). "In patients with type 1 diabetes, persistent unexplained hypoglycemic episodes at dawn together with reduced insulin requirement arouse souspicionof adrenal insufficiency." (PMID 34438593, 2021). "Type 1 diabetes (T1D) is a progressive heterogeneous autoimmune disease resulting in the destruction of insulin-secreting β cells by T cells." (PMID 33301420, 2021). "Type 1 diabetes (T1D) is a chronic autoimmune disease, characterised by progressive destruction of the insulin-producing β cells of the pancreas." (PMID 34876434, 2021). "Porcine islet xenotransplantation is a promising treatment for type 1 diabetes as an alternative to human pancreatic islet transplantation and long‐term insulin therapy." (PMID 34176167, 2021). "Our previous observations confirmed a progressive CHO/IR decline over time at each meal in women with type 1 diabetes under continuous subcutaneous insulin infusion (CSII) therapy during pregnancy." (PMID 33732212, 2021). "Transplantation of pancreatic islets containing insulin producing β cells has recently been used to cure type 1 diabetes." (PMID 33788062, 2021). "This is in line with the results of a Cochrane review by Fullerton showing only a minor (but clinically irrelevant) benefit of short-acting insulin analogues on HbA1c in people with type 1 diabetes (i.e. − 0.15% in favour of insulin analogues)." (PMID 34301317, 2021). "Most patients in INSTRIDE 1 were positive for total ADA, consistent with previous studies that have demonstrated a prevalence of insulin antibodies in patients with type 1 diabetes." (PMID 34174848, 2021). "Lachin JM, Genuth S, Cleary P. Retinopathy and nephropathy in patients with type 1 diabetes four years after a trial of intensive insulin therapy." (PMID 34320090, 2021). "The aim was to systematically review the efficacy and safety of sodium–glucose cotransporter inhibitor (SGLT2i) as an adjunct to insulin at different follow-up durations in randomized, double-blind clinical trials in patients with type 1 diabetes." (PMID 33651228, 2021). "Type 1 diabetes (T1D) is a chronic endocrine disease that results from autoimmune destruction of insulin-producing β-cells in the pancreas after the asymptomatic period of various duration." (PMID 34299114, 2021). "A meta-analysis examined the net impact of GLP-1 agonists on glycemic control, weight, and insulin dose in seven randomized controlled trials in 206 adult subjects with type 1 diabetes also treated with insulin over study durations of 3–15 months." (PMID 33828529, 2021). "Whilst progress has been limited, the evolving profile of a person with type 1 diabetes suggests that beyond ensuring accurate titration of exogenous insulin, efficient management of the disease should rely on other additional principles." (PMID 33595677, 2021). "The parents of children with type 1 diabetes also experience fear and distress during insulin injection and glucose testing procedures." (PMID 34356715, 2021). "This study examined the effects of swimming training combined with insulin therapy on the femoral midshaft structural and mechanical properties in growing rats with type 1 diabetes." (PMID 34440530, 2021). "Results with dapagliflozin, empagliflozin and sotagliflozin have indicated benefits of SGLT inhibition in managing type 1 diabetes when added to insulin." (PMID 33595677, 2021). "Individuals with type 1 diabetes have decreased BMD, possibly because of absolute insulin deficiency and the inability of exogenous insulin to emulate endogenous insulin secretion." (PMID 34200167, 2021).
type 1 diabetes (continued). "In type 1 diabetes, pancreatic islets are destroyed, and insulin stores are significantly reduced, which translates into a low/undetectable concentration of C-peptide in the serum." (PMID 34944607, 2021). "Type 1 diabetes (T1D) results from an autoimmune attack against the insulin-producing β-cells in the islets of Langerhans of the pancreas." (PMID 34712668, 2021). "The global rise in type 1 diabetes faces several challenges including the provision of insulin in underdeveloped and developing countries." (PMID 34961564, 2021). "In hyperinsulinemic euglycemic clamps, youth with type 1 diabetes are more insulin resistant compared to matched healthy peers and have lower functional exercise capacity, a marker of cardiovascular function and predictor of mortality." (PMID 33828529, 2021). "Type 1 diabetes (T1D) involves the criminal activity of murder of the insulin-producing pancreatic islet β cells." (PMID 34220832, 2021). "Induction of type-1 diabetes in the experimental animals resulted in significant reduction in serum values of insulin and c-peptide (p < 0.01 and p < 0.05, respectively) as compared to control animals." (PMID 34371877, 2021). "Type 1 diabetes (T1DM) is mainly caused by chronic autoimmune injury to pancreatic β cells, leading to an absolute deficit of insulin." (PMID 33883002, 2021). "Much research has focused on insulin and the autoimmune destruction of the beta cells involved in type 1 diabetes." (PMID 34405569, 2021). "Type 1 diabetes (T1D) is an autoimmune disease characterised by T cell-mediated destruction of the insulin-producing β cells in the pancreas." (PMID 35156097, 2021). "Type 1 diabetes is in relatively younger persons, who are insulin dependent and need to visit the health facility for management of their insulin treatment." (PMID 34147100, 2021). "In a recent study, valproic acid, a HDACi, was claimed to trigger the differentiation of adipose-derived stem cells into insulin-producing cells which were claimed to be clinically effective against type 1 diabetes." (PMID 34071497, 2021). "Before the discovery of insulin, children with type 1 diabetes became emaciated and often died within a year of diagnosis." (PMID 34717951, 2021). "With insulin treatment, the life expectancy of the people with type 1 diabetes has become comparably longer in relation to general population, which resulted in elevated burden of chronic life-threatening microvascular and macrovascular complications." (PMID 34671071, 2021). "C-peptide serves as the mediator in the correlation between the duration of type 1 diabetes and the required total insulin dose." (PMID 34959363, 2021). "In type 1 diabetes, residual endogenous insulin secretion was first shown to protect patients against development of DR." (PMID 34912295, 2021). "Intraportal allogeneic cadaveric islet transplantation is considered the best available treatment for patients with Type 1 Diabetes who cannot control their blood glucose levels with exogenous insulin, despite optimal intensive medical management." (PMID 33716982, 2021). "Type 1 diabetes is a condition that resulted from insufficient production of insulin by the pancreas while type 2 is due to improper utilization of produced insulin and ultimately leads to higher glucose levels in the circulatory system." (PMID 35127948, 2021). "Hepatic lipid synthesis is reduced in type 1 diabetic patients and in insulin-dependent diabetic mice, and insulin therapy was found to promote lipogenesis." (PMID 33667544, 2021). "The artificial pancreas is a closed-loop insulin delivery system that automatically regulates glucose levels in individuals with type 1 diabetes." (PMID 33770092, 2021). "The aim of this study was to establish the effect of this complex on glycaemic variability, insulin sensitivity and insulin dosing in obese children and adolescents with type 1 diabetes and MetS." (PMID 34684518, 2021).
type 1 diabetes (continued). "Blood glucose (BG) management is crucial for type-1 diabetes patients resulting in the necessity of reliable artificial pancreas or insulin infusion systems." (PMID 33726723, 2021). "In this manuscript, a recurrent neural network (RNN) based model for predicting upcoming blood glucose levels in people with type 1 diabetes is combined with several carbohydrate and insulin absorption curves in order to optimize the prediction results." (PMID 34450712, 2021). "Insulin therapy is the gold standard of treatment for type 1 diabetes and patients with advanced type 2 diabetes, but maintaining consistent blood glucose levels is challenging." (PMID 34444787, 2021). "Because our work is mainly focused on type 1 diabetes, we used either whole insulin or insulin β chain peptide 9-23 as antigens." (PMID 33868279, 2021). "Type 1 diabetes (T1D), also known juvenile-onset diabetes or childhood-onset diabetes, is a T cell-mediated autoimmune disease resulting in insulin-producing beta cell destruction in the islet." (PMID 34067829, 2021). "In INSTRIDE 1, patients with type 1 diabetes received MYL-1501D or insulin glargine over a 52-week period." (PMID 34174848, 2021). "People with type 1 diabetes are reliant on access to medical supplies such as insulin and blood glucose monitoring equipment." (PMID 33532617, 2021). "In recent years, the development of closed-loop systems, which link insulin delivery to sensor glucose levels, have started to transform management of type 1 diabetes." (PMID 33996702, 2021). "Dual‐hormone replacement therapy with insulin and amylin in patients with type 1 diabetes has the potential to improve glucose management." (PMID 34499434, 2021). "Diabetes is a chronic metabolic disorder defined by fasting hyperglycemia and is due to a deficit in insulin secretion by pancreatic β-cells of autoimmune origin for type 1 diabetes (T1D) or decompensated insulin resistance for type 2 diabetes (T2D)." (PMID 34441309, 2021). "Closed-loop glucose control, referred to as artificial pancreas, has emerged as the best solution to modulate insulin doses in response to blood glucose (BG) concentration in subjects with type 1 diabetes (T1D)." (PMID 33981286, 2021). "Type 1 diabetes is an immune-mediated disease, characterized by immune-cell targeting of the insulin producing beta cells of the pancreatic islets of Langerhans, leading to their demise and resulting insulin deficiency." (PMID 34691048, 2021). "In type 1 diabetes (T1D) there is a destruction of insulin producing cells as a consequence of an autoimmune response in which lymphocyte subpopulations are crucial." (PMID 34938295, 2021). "Type 1 diabetes is a chronic autoimmune disease characterized by the pancreas losing the ability to generate insulin, the hormone that regulates hyperglycemia." (PMID 33810048, 2021). "Type 1 diabetes (T1D) is a chronic illness that requires intensive lifelong management of blood glucose concentrations by means of external insulin administration." (PMID 32440803, 2021). "Participants with type 1 diabetes in a previous study described insulin as “life or death” for them, but this analysis shows that the general public also appreciates the life-saving nature of insulin." (PMID 33496671, 2021). "The study adopts an open-label, multinational, multicentre, randomised, crossover design and aims to randomise 72 children aged 1–7 years with type 1 diabetes on insulin pump therapy." (PMID 33579766, 2021). "Type 1 diabetes mellitus (T1DM) is a polygenic disease characterised by autoimmune destruction of the insulin producing beta cells in the pancreas which subsequently leads to hyperglycaemia." (PMID 33933144, 2021). "Pancreatic islets transplanted into portal vein can induce focal hepatic steatosis in type 1 diabetes recipient, which indicates that insulin secretion promotes local fat deposition." (PMID 34123402, 2021).
type 1 diabetes (continued). "Detailed metabolic analyses revealed 12–61% and up to 20% lower whole-body (skeletal muscle) and hepatic insulin sensitivity, respectively, in type 1 diabetes (T1D), depending on the population studied." (PMID 34071554, 2021). "Collectively, these findings suggest that improvements in glycemic outcomes and changes in sleep accompany hybrid close loop insulin delivery in adults with long standing type 1 diabetes and hypoglycemia unawareness." (PMID 33628834, 2021). "Type 1 diabetes (T1D) is a chronic immune-mediated disease characterized by destruction of β cells, the insulin-producing cells in the pancreas." (PMID 33604389, 2021). "Type 1 diabetes is a chronic autoimmune disease, characterized by the immune-mediated destruction of insulin-producing β cells of pancreatic islets." (PMID 34702762, 2021). "Type 1 diabetes is most common among children, adolescents, and young adults but is treatable and manageable through the daily intake of insulin by those diagnosed with the disease." (PMID 34463627, 2021). "This was a population-based cohort study that followed 557 patients, 51% to 51.8% males, with “younger onset” type 1 diabetes, who were diagnosed and had received insulin therapy before the age of 30." (PMID 34357132, 2021). "Type I diabetes mellitus (T1DM) is an autoimmune-related disorder characterized by the destruction of insulin-producing beta cells in the pancreatic islets of Langerhans." (PMID 34229671, 2021). "Whilst these strategies have been effective at maintaining insulin levels, the removal of the necessity of such injectable insulin therapies would be greatly beneficial to the treatment of type 1 diabetes." (PMID 34572086, 2021). "Autoimmune destruction of insulin-producing B cells in the pancreas results in type 1 diabetes, a disease condition that demands more than a mere administration of exogenous insulin to gently and sensitively regulate blood glucose concentration." (PMID 33859701, 2021). "This in line with the results of a global survey of 1478 individuals with type 1 diabetes, and their care providers reported that 25.9% of the respondents from the United States had rationed their insulin at some point in the last year." (PMID 33496671, 2021). "Still, the main aim when managing diabetes type 1 remains glycemic control—to avoid complications such as diabetic neuropathies—which is mostly achieved by insulin regulation." (PMID 31991895, 2020). "The gluconeogenic conversion of protein-derived and free amino acids into glucose during exercise is upregulated in type 1 diabetes if insulin is withheld." (PMID 32533229, 2020). "For patients with Type I diabetes, blood sugar levels are usually required at least twice daily, and insulin must be administered, usually by nursing staff." (PMID 32917193, 2020). "An important issue in managing juvenile diabetes is related to the physical pain and inconvenience experienced in each measurement of blood glucose and each insulin administration." (PMID 33023137, 2020). "The objective was to develop a personalized health model that can automatically detect the incidence of infection in people with type 1 diabetes using blood glucose levels and insulin-to-carbohydrate ratio as input variables." (PMID 32784179, 2020). "Individuals with insufficient production of insulin develop type 1 diabetes, a condition that was fatal before the introduction of purified insulin as a treatment strategy many decades ago." (PMID 32372975, 2020). "For type 1 diabetes (T1D), this is due to autoimmune-mediated destruction of the pancreatic islet compartment leading to deregulation of glucose-responsive insulin production from beta cells." (PMID 32152396, 2020). "In patients with type 1 diabetes, higher basal insulin dosage seems to be related with an impairment of pulmonary function." (PMID 32344939, 2020).